RNU6-1022P (RNA, U6 small nuclear 1022, pseudogene)
Gene: Small nuclear RNA gene on chromosome 1 (21,987,816 to 21,987,919, forward strand). Ensembl gene ENSG00000201919.
Homologues: Orthologues: chimpanzee U6 (96% identical), mouse Gm25039 (88% identical), macaque U6 (82% identical), guinea pig U6 (67% identical). Paralogues in human: RNU6-776P (95% identical), RNU6-797P (91% identical), RNU6-1309P (88% identical), RNU6-454P (88% identical), RNU6-1047P (87% identical), RNU6-1091P (87% identical), RNU6-697P (87% identical), RNU6-727P (87% identical), RNU6-742P (87% identical), RNU6-938P (87% identical), RNU6-1083P (86% identical), RNU6-1123P (86% identical), and 1287 more.